FAS (Fas cell surface death receptor)
Diseases named in the same sentence as FAS in open-access papers (continued):
Sharing a sentence is not in itself a finding about the gene and the disease.
tumor (continued). "Paradoxically, FAS is essential in tumor growth, although whether this function of FAS is dependent on a particular isoform is unknown." (PMID 23758675, 2013). "The expression of FAS on tumor cells, if downstream signaling pathways are functional, may assist FAS-triggered killing of tumors by immune-effector cells." (PMID 23326385, 2013). "Studies suggest that down-regulation of the FAS gene may protect tumor cells against elimination by anti-tumor immune responses." (PMID 24014103, 2013). "IFNγ increases tumour cell surface expression of FAS and lymphocyte Tγδ cytotoxicity." (PMID 23226965, 2012). "The induced sensitivity of tumor cells to FAS-mediated killing represents a TCR-independent mechanism for tumor cell killing and can function as a more potent cytotoxic modality especially in instances where TCR affinity is low and perforin-mediated cytotoxicity is less efficient." (PMID 23087904, 2012). "The upregulation of FAS expression on NK cells has been shown to be mediated by IL-12 and could account for some of the enhanced tumor killing response." (PMID 20946663, 2010). "In addition, FAS-L expression was clearly attributed to the tumor cell surface in liver metastases shown by immunohistochemistry, while FAS expression was observed predominantly on CD8+ T cells infiltrating the perimetastatic site." (PMID 20205946, 2010). "FAS is highly expressed in normal human colonic epithelial cell and its expression is progressively decreased during tumour progression from normal epithelium to adenocarcinoma in about 50% of the cases, whereas FASL has been shown to be upregulated early during colon carcinogenesis." (PMID 17551494, 2007). "Furthermore, variations in patient populations, including differences in tumor stage, histological subtype, or demographic factors like age and smoking status, could contribute to variability in FAS deletion prevalence across studies." (PMID 39416461, 2024). "High FAS expression could indicate an increased capacity for apoptosis in some tumors, possibly serving as a mechanism for tumor suppression, while lower levels of FAS contribute to apoptosis evasion, facilitating tumor progression and resistance to cell death." (PMID 39416461, 2024). "The resulting Sp1-HDAC1 complex deacetylates H3K56 (histone H3 lysine 56), silences FAS and MIR146A genes and upregulates miR-146a targets such as interleukin-1 receptor-associated kinase 1 (IRAK1) and the chemokine receptor CXCR4, and ultimately promotes tumor invasion, proliferation, and survival." (PMID 37174034, 2023). "Similarly, the absence of a functional mutation in the FAS gene in tumor cells helps tumor cells escape CD95L/FasL-binding-activated apoptosis." (PMID 37078002, 2022). "Similarly, FAS/FAS-L interaction also shows both pro- and anti-tumor activities." (PMID 35746487, 2022). "Thus, simultaneous loss or downregulation of FAS and upregulation of FASL on tumor cells might contribute to tumor evasion of immune−mediated cytolysis." (PMID 36426359, 2022). "In our tumor model, we found that taxifolin treatment led to reduced expression of genes encoding fatty acid synthesis-related proteins C/EBPa, PPARγ, FABP4, and FAS, suggesting that tumor cell lipid synthesis was reduced and that this may have contributed to the inhibition of tumor growth." (PMID 34462635, 2021). "To investigate whether we could further enhance FAS levels on the tumor cells, we combined the KDM1A inhibitor treatment with low-dose irradiation (2 Gy), but the combination therapy did not induce higher FAS expression levels than KDM1A inhibitor treatment alone." (PMID 34771652, 2021). "The specific inhibition of FAS gene could lead to apoptosis of tumor cells." (PMID 33763366, 2021). "Furthermore, FASL gene up-regulation may increase the ability of tumor cells to counter-attack the immune system via inducing apoptosis of FAS-sensitive lymphocytes." (PMID 24014103, 2013).
tumor (continued). "Additionally a further feature of tumor immune escape mechanisms, the FAS/FAS-L "counterattack", could be shown in the described murine model." (PMID 20205946, 2010). "Moreover, an agonistic anti-FAS mAb enhanced apoptosis in primarily cultured tumour cells." (PMID 17551494, 2007). "Simultaneously, RT upregulates FAS (death receptor), MHC class I, translocation of calreticulin to tumor cell surfaces, and increases the release of HMGB1 from dying tumor cells." (PMID 40141437, 2025). "Cytokine treatment significantly increased the expression of FAS, TRAIL-R2, and ICAM-1 in all BC cell lines, enhancing NK cell-mediated apoptosis and promoting NK cell-tumor cell conjugate formation." (PMID 41102150, 2025). "Most of the 313 new disease links belonged to the DisGeNET class neoplasms (n = 40; EGFR, ERBB2, KITLG, AREG) but also to immune diseases (n = 29; FAS), neurological diseases (n = 13; PNPLA6), and cardiovascular diseases (n = 13; CD163)." (PMID 40593564, 2025). "Some studies suggest that oleic acid induced cancer cells led to increase the expression of SREBP1, FAS, and SCD‐1 and induce tumor progression in hepatocarcinoma cells." (PMID 39425259, 2025). "Immunofluorescence analysis confirmed the coexpression of CXCR2, CXCL15, FAS, and ELOVL5 within the tumours." (PMID 41163221, 2025). "This cytotoxic activity relies on the ability of radiation to upregulate class II MHC molecules as well as the death receptors FAS/CD95 and DR5 on the surface of tumor cells." (PMID 40918097, 2025). "The higher the tumor volume in the RLS40 control subgroups, the lower the percentage of FAS+ neutrophil population: 20.6 ± 1.9% in the RLS40Low subgroup and 1.4 ± 0.1 and 2.8 ± 0.3 in RLS40Med and RLS40High subgroups, respectively." (PMID 40867260, 2025). "Based on these findings, 11 pairs of tumor and adjacent tissues before RFA and after RFA were collected for assessing mRNA expression of APC, FAS, HGF, PCNA and EFCAB7." (PMID 39276379, 2024). "Tumor-derived EVs can also carry FASL, which induces apoptosis in T cells and NK cells via the FAS-FASL pathway, further diminishing antitumor responses." (PMID 39684559, 2024). "On the other hand, pRCC showed upregulation of TFPI2, FSTL1, FAS, and PIGR in the epithelial/tumor, C1QTNF3 and GRN in the endothelial, and ITGAX, HLA-DQA1, IL4I1, and CTSC in the immune compartments." (PMID 38703764, 2024). "While anti-PD1 ICI is thought to activate CD8+ T cells to target the tumor through MHCI interactions, CD4+ T cells can kill MHCII+ cells though FAS/FASL interactions." (PMID 38265267, 2024). "MHC-I is expressed in almost all nucleated cells, and CD8+ T cells recognize tumor cells by recognizing peptide MHC-I complexes generated by the MHC-I antigen presentation pathway and killing these cells via perforin- or FAS-dependent pathways." (PMID 39263534, 2024). "In tumor progression, the level of soluble FASL increases, which inhibits FAS-mediated tumoricidal activity of cytotoxic T lymphocytes and NK cells and decreases FAS receptor expression levels." (PMID 38791085, 2024). "PD-L1+, FAS+ and CD73+ tumor cells were found at higher frequencies within MSLN+ SKOV-3 cells compared with MSLN- SKOV-3 cells, regardless of treatment group M28z and MBBz." (PMID 36746513, 2023). "We further analyzed the tumor supernatants of both tumor types treated with MK2 KO CD8+ T cells compared to control and treated with WT CD8+ T cells and found soluble FAS and GZMB to be increased." (PMID 37415974, 2023). "Conversely, in the absence of HER2-signaling-phosphorylated Sp1, HDACs tend to combine with S100 and upregulate the expression of FAS and MIR146A genes, contributing to tumor suppression." (PMID 37174034, 2023). "HAT1 also functions as a transcription factor to regulate the tumor microenvironment, sensitivity to immunotherapy, and the expression of various genes, such as BCL2L12 and FAS." (PMID 37513949, 2023).
tumor (continued). "The TME contains various signaling molecules that can alter lipid metabolism in TAMs, including increased lipid uptake, FAS, and FAO, which promote TAM polarization to the pro-tumor M2 phenotype." (PMID 37700339, 2023). "The balance of tumor immunity is towards antitumor due to the upregulated expression of tumor antigens, FAS, TRAIL receptors, MHC class I on tumor cells and granzymes, IL-1, IL-12, TNF-α, IFN-α/β/γ, and perforin in TME." (PMID 37345046, 2023). "The critical role of DNL enzymes in regulating tumorigenesis has been shown through genetic evidence from several studies including the knockdown of ACLY, ACC, FAS, and SCD in various tumor types." (PMID 37958642, 2023). "We further analyzed the tumor supernatants of tumors treated with Th2 cells compared to control and found soluble GZMB and FAS to be increased." (PMID 36376448, 2023). "The upstream regulator analysis of cisplatin revealed an increase in FAS, BTG2, SESN1, and CDKN1A, and the involvement of the tumor microenvironment pathway." (PMID 38003016, 2023). "We observed in multivariate Cox analysis that patients with the FAS c.-671GG genotype had lower EFS and OS than those with the remaining genotypes and nearly two times more chances of presenting tumor progression, relapse of the tumor, or death than others." (PMID 37798436, 2023). "This is due to the processes by which CAR-NK cells operate: natural cytotoxicity in case of downregulated expression of targeted tumor antigens, ADCC effect, TNF-related apoptosis-inducing ligand (TRAIL), and FAS/FASL." (PMID 36499331, 2022). "Compelling and emerging experimental data indicates that the FAS acts as a tumor suppressor in human cancer and is essential for CTL effector function in the suppression of tumor development." (PMID 35053524, 2022). "To examine which transcription factor regulates the expression of FAS, TRAIL, and DR5, we surveyed the changes in the expression levels of certain transcription factors and tumor suppressor miRNAs by Western blot and qRT-PCR, respectively." (PMID 35428370, 2022). "FOXOs are discovered as a tumor suppressor through activating G2/M arrest related genes CDKN1A and GADD45A, apoptosis related genes FAS, DR4 and DR5, respectively 58-62." (PMID 35813464, 2022). "The qRT-PCR results revealed that AXL (p = 0.0308), FAS (p = 0.0134), TNFRSF1B (p = 0.0250), and CDKN2A (p = 0.0224) mRNA expression were considerably greater in tumor tissues." (PMID 36186479, 2022). "It was reported that STAT3 can induce abnormal proliferation of tumor cells through regulation of BCL-2, FAS, survivin and CyclinD1." (PMID 35513871, 2022). "The FAS/FAS-L interaction in Bregs induces apoptosis in CD4+ T cells, while the same interaction also helps in killing tumor cells." (PMID 35746487, 2022). "GEGFR, CD40, SPATA2, ZBP1, ID1, and MYC showed a significant CNV amplification in most tumour types; however, TLR3, PDHB, FAS, and MAP3K showed a significant CNV deletion in most tumour types." (PMID 36186436, 2022). "In complete agreement with our epigenetic profiling data, gene expression of FAS, FASLG, TNFSF10, TRAF1 and TRAF2 was higher in the clusters corresponding to dysfunctional tumor-infiltrating CD8+ T cells." (PMID 35668194, 2022). "In this signature, up-regulated DKK1 and GRP together with down-regulated FAS and CD1B had significant correlation with tumor stage, metastasis and lymphatic invasion." (PMID 33996273, 2021). "NK cells can destroy tumour cells by inducing death receptor-mediated apoptosis upon engagement of TRAIL and FASL with their receptors, TRAIL receptor (TRAILR) and FAS, respectively, at tumour target cells." (PMID 34885119, 2021). "Mechanisms through which CTCs can escape from immune cells include the expression of PD-L1 and CD47 and the alteration of FAS/FASL, which can promote T cell apoptosis or protect tumor cells from apoptosis." (PMID 34830787, 2021).
tumor (continued). "The coincident antigen-specific upregulation of FAS/FASL and PD-1/PD-L2 on T cells and CAFs, respectively, drives the death and dysfunction of tumor-specific T cells, resulting in enhanced tumor viability." (PMID 34305902, 2021). "Cell division cycle 25C (CDC25C) can inhibit apoptosis in various tumor types, including NSCLC, through regulation of the G2/M-phase transition and FAS pathway." (PMID 33988228, 2021). "The observation that knocking out FAS pathway genes results in faster proliferation in some AML cells, and their signature as putative tumor suppressor genes, is therefore very unexpected." (PMID 34764293, 2021). "The cytotoxic activity was mediated by the upregulation of MHC II molecules and death receptors FAS/CD95 and DR5 on the surface of tumor cells." (PMID 34068491, 2021). "In vivo, RT can play the dual function of regulating the expression of the Fas Cell Surface Death Receptor (FAS) and MHC class I molecules on the tumor cells on one hand, and modulating MHC class I-mediated antitumor immunity on the other hand." (PMID 32340275, 2020). "IR also increases death receptors such as FAS and TRAIL on tumor cells, enhancing malignant cell destruction by NK cells." (PMID 32612950, 2020). "It belongs to the tumour necrosis factor (TNF) family, and binds to its receptor FAS on different cells and tissues, including tumour cells and immune cells, i.e. both FASLG and FAS can be expressed by the cytotoxic T lymphocytes." (PMID 32606315, 2020). "CCL5, secreted by tumor-infiltrating CD4 T cells, also facilitates the FAS-FASLG mediated CD8 T-cell apoptosis in gastric cancer." (PMID 33381115, 2020). "The traditional, tumor-cytotoxic N1 phenotype has the potential to kill tumor cells, due to elevated levels of immune-activating factors (e.g., TNF-α, ICAM-1, FAS) and direct antibody-dependent cytotoxicity." (PMID 33171818, 2020). "Both FAS and FASLG are important in cancer cell immunity as they have been seen to have both tumorigenic and tumour suppressive roles." (PMID 32606315, 2020). "RT can change the immunosuppressive tumor environment by triggering expression of MHC class I, NKG2D ligands, or FAS/CD95 on tumor cells." (PMID 31179236, 2019). "The tumor cells escape from apoptotic cell death via immunosuppressive networks 45, including up-regulation of FASL as well as down-regulation of FAS expression on tumor cells." (PMID 31754376, 2019). "Reduced FAS expression and/or increased FASLG expression facilitate tumor development and progression by inhibiting tumor cell apoptosis or by inducing immune cell apoptosis." (PMID 29950587, 2018). "Another mechanism by which RT-induced VEGF-A secretion can enhance a pro-tumor environment is through its influence on endothelial cells by inducing expression of CD95L (or FasL), the ligand for FAS." (PMID 30766539, 2018). "Although FASL-mediated killing is often indiscriminate due to rather ubiquitous expression of FAS on mammalian tissues, TRAIL-mediated cytotoxicity is more selective toward virally infected cells and tumor cells, making it a potential target in immunotherapy." (PMID 29326711, 2017). "RT is able to induce upregulation of major histocompatibility complex class I molecules, FAS/CD95, and stress-induced natural killer group 2D-ligands on tumor cells by enhancing recognition and killing of tumor cells by CTls." (PMID 29100279, 2017). "In an in vitro assay, we found that the anti-tumor mechanism of SB was due to P38/SIRT1-regulated cell apoptosis through G2/M phase arrest and ER stress-, intrinsic mitochondrial-, and extrinsic FAS/FASL-mediated pathways." (PMID 29312612, 2017).
tumor (continued). "FAS (CD95) engagement is one mechanism by which immune cells kill virus-infected cells and tumor cells." (PMID 28837681, 2017). "Endothelial cells in the tumor vasculature express the FAS ligand, which kills the TME-infiltrating T cells that express FAS." (PMID 27259252, 2016). "However, no studies have investigated whether tumor sites contribute to the association between FAS/FASL polymorphisms and risk for second primary malignancy (SPM)." (PMID 26858129, 2016). "The non-immunogenic properties of apoptotic cells can be hijacked by tumor cells to escape immune detection by creation of a local immunosuppressive environment that is defined by the presence of IL-10, TGF-β, soluble FAS and FAS-ligand." (PMID 26915293, 2016). "Among the most downregulated proteins, we found several confirmed or candidate tumour suppressor genes (eg, ID1, FAS, FPR1, IL10, PCGF2, VDR)." (PMID 25594007, 2014). "On the other hand, we found FAS, FPR1, ID1, IL10, PCGF2, VDR among downregulated proteins: all are involved in tumor immune-escape through induction of apoptosis and anti-inflammatory activities." (PMID 25594007, 2014). "Alteration of FAS and FASL gene expression decreases cellular apoptotic capacities, allowing many tumor cells to evade or suppress the immune system." (PMID 24014103, 2013). "Also, decreased FAS expression may protect transformed cells from being eliminated by anti-tumor immune responses, whereas heightened FASL expression may increase the ability of tumor cells to counter-attack the immune system by killing FAS-sensitive lymphocytes, contributing to cancer development." (PMID 24014103, 2013). "Prior work had shown that CD95/FAS can, in some contexts, function upstream of NFκB to promote cell survival and tumor growth." (PMID 22970367, 2012). "Ewing's sarcoma family of tumour cells and tumour samples express both TRAIL DR and FAS, although p75NTR has only been examined in cell lines." (PMID 20877355, 2010). "FAS expression in the primary cultures (PAP60 and MIH55) resembled that of the parental tumours and was significantly altered in xenograft models only in the case of PAP60 primary culture where it was downregulated by twofold." (PMID 17551494, 2007). "IFN-γ triggers the transcription of key anti-tumour genes, including major histocompatibility complex class I, FAS, CASPASE-1, and growth-inhibitory genes, via IFNGR1-mediated JAK-STAT signalling, thereby enhancing immune cell activation and tumour cell apoptosis." (PMID 40657375, 2025). "Inhibition of FAS reduces fatty acid synthesis and induces malonyl-CoA accumulation, thereby inhibiting carnitine palmitoyltransferase 1 (CPT1)-mediated FAO, leading to cell cycle arrest and apoptosis in tumor cells." (PMID 40137165, 2025). "scRNA-Seq data showed that tumor-promoting genes associated with cell proliferation, stemness, metastasis, drug resistance, and key transcription factors (TFs) were upregulated in OX40+ ECs from CRC tissues, whereas important tumor suppressors, including RB, BAD, and FAS, were markedly reduced." (PMID 40026246, 2025). "miR-483-5p overexpression was demonstrated to promote tumor growth in PCa cells by suppressing RBM5, a tumor suppressor gene that modulates apoptosis by regulating the alternative splicing of critical apoptotic mediators, including FAS and caspase-2." (PMID 41136394, 2025). "During tumor progression, increased secretion of TGF-β in tumor cells, as well as paracrine secretion from surrounding stromal cells, stimulates tumor invasiveness and metastasis followed by immunosuppression, which is mediated by the FASL/FAS system." (PMID 38791085, 2024).